CSF1R (colony stimulating factor 1 receptor)
Diseases named in the same sentence as CSF1R in open-access papers (continued):
Sharing a sentence is not in itself a finding about the gene and the disease.
tumor (continued). "CSF1R activation leads to the recruitment of CSF1R-expressing macrophages that constitute a large part of the tumor mass in dt-GCT, thus making this pathway an ideal therapeutic target for compounds interfering with the CSF1/CSF1R-signaling axis." (PMID 28716061, 2017). "In a preclinical PCa animal model, the CSF1R blockade was shown to restrict the local expansion of MDSCs, thus maintaining the immune surveillance against tumor growth." (PMID 29142311, 2017). "Colony-stimulating factor 1/CSF1-R signaling drives the recruitment and the differentiation of TAMs toward a M2 phenotype in tumor." (PMID 28769933, 2017). "Sulfatinib, a potent oral kinase inhibitor targeting VEGFR, FGFR1, and CSF1R with good selectivity, has demonstrated anti-angiogenic and anti-tumor activity in preclinical studies (Hutchison MediPharma, unpublished data)." (PMID 28159938, 2017). "CSF-1/CSF-1R signaling has been shown to play essential roles in regulating differentiation and survival of macrophages and driving macrophage recruitment into tumor tissues." (PMID 28424405, 2017). "provided evidence that PDAC tumor cells overexpressed M‐CSF, which resulted in the activation of CSF1R in macrophages and subsequent M2 transformation." (PMID 28097809, 2017). "Regorafenib is a different oral MKI that potently blocks multiple protein kinases involved in tumor angiogenesis (VEGFRs 1–3, TIE2), oncogenesis (KIT, RET, RAF-1, BRAF), metastasis (VEGFR3, PDGFR, fibroblast growth factor receptor), and tumor immunity (CSF1R)." (PMID 29291014, 2017). "More recently, PGE2 has also been identified as a tumor-induced immunosuppressive factor, able to mediate the reprogramming of the tumor microenvironment, or as a direct modulator of macrophage activity by transactivation of CSF-1R." (PMID 28415726, 2017). "Depletion of CD115+ F4/80+ macrophages during early hyperplastic stage with anti-CSF-1R antibody (M279) reduced primary tumor growth and lung metastasis." (PMID 28197019, 2017). "We show a change in expression of p-AKT, FAK, and PD-L1 markers in macrophages from tumor treated with CSF1R inhibition in the setting of adaptive resistance, as compared to samples that continued with only anti-VEGF therapy." (PMID 29228548, 2017). "More recently, two studies demonstrated that the CSF1R and IL-6 pathways play critical roles in the migration of MDSCs to tumours microenvironments." (PMID 27368058, 2016). "Our previous study illustrates that depleting bone marrow-derived myeloid cells through CSF1R blockade, significantly decreased recruitment of BMDCs from bone marrow to the tumor site." (PMID 28149704, 2016). "Here, we demonstrated that anti-PD-1 antibody as a single treatment failed to control tumor growth, whereas the combination treatment with CSF-1R inhibitor BLZ945 showed superior tumor reduction." (PMID 28123870, 2016). "Of note, anti‐CSF1R therapy appears to be dependent on the M1/M2 macrophage ratio within a given tumor." (PMID 26666269, 2016). "Inhibition of CSF1R was found to promote efficient depletion of macrophages and significantly delay tumor regrowth following irradiation." (PMID 27516055, 2016). "In these studies, administration of the CSF-1R inhibitor GW2580 to tumor bearing mice drastically reduced the numbers of CD11bloF4/80hi macrophages in S phase." (PMID 26884646, 2016). "Previous efforts have sought to recreate a similar pro-inflammatory microenvironment by personalized vaccinations of irradiated tumor cells transduced with stimulatory B7-2 and GM-CSF genes or, conversely, by inhibiting M2 growth via CSF-1R inhibition." (PMID 27092773, 2016). "This latter effect correlated with changes in the number of the CSF-1R expressing cells represented in the excised tumor masses treated with the inhibitor, in combination with cisplatin." (PMID 27486763, 2016).
tumor (continued). "The association of increased macrophage infiltration with poor diagnosis in many types of cancers has led to some interest in targeting CSF-1R for cancer therapy, and studies have shown that CSF-1R inhibitors have anti-tumor effects." (PMID 27576527, 2016). "Since PI3K p110δ is a critical mediator of CSF-1-induced macrophage motility, signaling downstream of the CSF-1R is therefore integral to the promotion of tumor cell invasion by BMM." (PMID 31453214, 2016). "Two trials are using ICB in the context of strategies aiming at targeting the tumor microenvironment, namely using a CSF1-R inhibitor (NCT02526017) or a TGFβ receptor I kinase inhibitor (NCT02423343)." (PMID 28003994, 2016). "To compare TAMs infiltration in different tumor groups, we analyzed the presence of TAMs in single-cell suspensions from tumor tissues by flow cytometry assay for CSF-1R and F4/80 staining, two well-characterized markers of TAMs." (PMID 27541266, 2016). "This study provides proof-of-principal that blockade of the CSF-1/CSF-1R pathway results in fewer macrophages recruited to human breast tumors, and this change in myeloid recruitment affects the overall composition of the tumor microenvironment." (PMID 26884646, 2016). "Other groups have shown that decreasing the number of tumor macrophages by targeting CSF1R has proven to be an effective combination with both chemotherapy and radiation therapy." (PMID 27602953, 2016). "Macrophage depletion with a diet containing the CSF-1R specific kinase inhibitor Ki20227 following surgery significantly reduced postoperative tumor recurrence and abrogated enhanced metastatic outgrowth." (PMID 25762633, 2015). "On the therapeutic front, we report that PLX3397, a potent tyrosine kinase inhibitor that targets CSF-1R, inhibits the immunosuppressive tumor milieu and facilitates immune responses, resulting in improved antitumor T-cell function." (PMID 25939769, 2015). "Meanwhile, overexpression of CSF1 receptor (CSF1R) positive cells has been observed in tumorous tissues and high expression levels of CSF1 mRNA in PVNS." (PMID 25854167, 2015). "This is in accordance with previous reports describing CSF1 (ligand) expression in tumour cells but the receptor, CSF1R, in the surrounding TAM populations." (PMID 26066800, 2015). "After binding to colony-stimulating factor 1 receptor (CSF-1R) on macrophages, M-CSF can activate macrophages, promoting secretion of growth factors that are essential for the pre-metastatic niche and tumor growth or metastasis." (PMID 26021873, 2015). "Previous studies have detected anti-tumour activity after disrupting the CSF1/CSF1R signalling pathway, probably as a result of blocking the recruitment and inhibiting the activation of TAMs." (PMID 26066800, 2015). "Combining anti-CTLA-4 and anti-PD-1 with a CSF-1R inhibitor shows profound synergy with a significant reduction in tumor burden." (PMID 26500653, 2015). "PLX3397, a potent tyrosine kinase inhibitor of CSF-1R, enhanced the efficacy of immunotherapy by decreasing macrophage infiltration and activating tumor-infiltrating lymphocytes." (PMID 25125485, 2014). "TAM depletion by clodrolip or a CSF-1R inhibitor increased the anti-angiogenic and anti-tumor effects of VEGF-VEGFR2 antibodies." (PMID 25051364, 2014). "The treatment of cell with CSF-1 mimicked the presence of macrophages in the tumor microenvironment, as our previous findings have demonstrated that the presence of macrophages in the tumor microenvironment increases CSF-1R expression in cancer cells." (PMID 23561040, 2013). "Activation of CSF-1R by its ligand is likely to occur in an autocrine manner in tumor cells in which CSF-1R and CSF-1 are co-expressed, or in paracrine manner, when CSF-1R is stimulated by CSF-1 released by fibroblasts." (PMID 23561040, 2013). "CSF-1 recruits peripheral macrophages to the tumor site via CSF-1 receptor (CSF-1R) and is vital to induction of M2 phenotype." (PMID 24202450, 2013).
tumor (continued). "For the EGF-CSF1 paracrine loop, a blocking antibody to the CSF-1R decreased in vivo invasion in the YB strain, indicating that in vivo invasion of the YB tumor cells was still dependent upon the EGFR-CSF-1R paracrine loop interaction with macrophages." (PMID 22314082, 2012). "Oncogenic signals emanating from an aberrantly expressed CSF-1R in tumor cells promote tumor growth and metastasis in breast and ovarian cancers." (PMID 22028782, 2011). "The candidate substrates identified in our analysis (e.g. p120, integrin β4, plakophilin 3, STAT3 and vimentin) will inform future studies addressing the mechanisms involved in CSF-1R-induced tumor progression." (PMID 21049007, 2010). "Colony stimulating factor-1 receptor (CSFR1) is involved in tumour cell invasion and migration, and high level expression is associated with poor prognosis in cancer patients." (PMID 17242701, 2007). "CSF1 binding to CSF1R activates kinase signaling pathways that drive tumor growth." (PMID 40392406, 2025). "Blocking the CSF1/CSF1R pathway suppresses macrophage migration into tumor tissue." (PMID 39941714, 2025). "CSF1R, a class III RTK, is well known for regulating the survival, proliferation, and differentiation of mononuclear phagocytes and has been implicated in immune modulation and tumor progression through macrophage recruitment and polarization." (PMID 41313502, 2025). "The efficacy of CSF-1R inhibition appears to be influenced by tumor molecular subtypes." (PMID 40427130, 2025). "Both subtypes share the potential to benefit from CSF-1R inhibitors and other strategies aimed at repolarizing TAMs to the M1 phenotype, which could shift the tumor from cold to hot, enhancing the effectiveness of immunotherapies." (PMID 40281554, 2025). "Similarly, TAM-targeted approaches, such as CSF-1R inhibition or PI3Kγ-driven reprogramming, are discussed to address anti-tumor immunity suppression." (PMID 40422244, 2025). "CSF1R, paradoxically associated with favorable prognosis in DLBCL, remains a therapeutic target for reprogramming M2-tumor-associated macrophages (TAMs), as shown by SYHA1813’s (a VEGFR and CSF1R inhibitor) efficacy against Bruton’s tyrosine kinase inhibitor (BTKi) resistance." (PMID 40186663, 2025). "However, the response to CSF1R inhibition can vary depending on tumor type, TAM heterogeneity, and compensatory mechanisms." (PMID 40821795, 2025). "In contrast, in a RAS-driven model, CSF-1R depletion accelerated tumor growth." (PMID 40642066, 2025). "While literature exists on CSF-1R or myeloid inhibition and brain lesions, the findings vary depending on tumor type, metastasis assay (hematogenous, intracranial implantation), inhibitor, dose, and schedule, with the latter often including pretreatment regimens." (PMID 40760255, 2025). "Thus, inhibition of CSF-1R signaling blocked the ability of macrophages to enhance tumor cell trans-endothelial migration." (PMID 40646332, 2025). "In terms of blocking tumor-promoting signals and repolarization of TAMs, inhibition of the CSF-1R has been shown to preferentially eliminate macrophages with an inflammatory signature but spare macrophage populations expressing proangiogenic/cancer genes in mice and humans." (PMID 40508145, 2025). "Macrophages, particularly M2 macrophages, have a unique inhibitory role in the tumor microenvironment, and the colony-stimulating factor 1 (CSF-1) receptor (CSF-1R) plays a crucial role in the recruitment and differentiation of monocytes into pro-tumor M2 macrophages and their survival." (PMID 41247642, 2025). "TRPC tumor immune infiltrates exhibited increased expression of CSF1R compared to the TSC group." (PMID 40661379, 2025). "The CSF1R inhibitor pexidartinib was reported in a model of malignant melanoma to eliminate TAMs and induce differentiation into M1-like macrophages, leading to an increase in and activation of tumor-infiltrating T cells." (PMID 40940867, 2025).
tumor (continued). "CSF1R expression is restricted to macrophages at the tumor site, indicating that CSF1 may promote metastatic potential by regulating the infiltration and function of TAMs." (PMID 40453088, 2025). "This includes blocking “do not eat me” signals like CD47-SIRPα or CD24-Siglec-10 to enhance phagocytosis by macrophages, inhibiting monocyte recruitment or differentiation via pathways like CSF-1/CSF-1R, or attempting to repolarize M2-like TAMs towards an anti-tumor M1-like state." (PMID 40458806, 2025). "Unless the CSF-1R expression of brain and tumor cell types changed between in vitro and in vivo conditions in a manner that we could not discern, the data suggested that alterations in factors secreted by myeloid cells may be responsible." (PMID 40760255, 2025). "The small molecule CSF1R antagonist named PLX3397 (Pexidartinib), has been found to penetrate the blood-brain barrier and significantly reduce the amount of tumor-associated microglia, thereby preventing tumor invasion in a glioblastoma mouse model." (PMID 40083710, 2025). "Deletion or therapeutic inhibition of Csf1r reduced the tumor burden in these mice." (PMID 39425000, 2025). "This strategy could enhance the efficacy of immunotherapies by increasing tumor immunogenicity, thereby improving responsiveness to treatments such as immune checkpoint inhibitors and macrophage-targeted therapies, including CSF1R and TREM2 inhibitors." (PMID 40330466, 2025). "However, macrophage-mediated trans-endothelial migration of tumor cells was decreased in the presence of either a CSF-1R blocking antibody or a small molecule inhibitor of CSF-1R." (PMID 40646332, 2025). "Study shown that the specific targeting of the CSF1R significantly inhibits tumor growth in mice with EL4 tumor and mouse mammary tumor virus transgenic mammary tumor model by depleting M2-type macrophages, indicating a promising target for cancer immunotherapy." (PMID 41019045, 2025). "The data, while in vitro, support the novel hypothesis that microglia, by their secretion patterns, orchestrate a complex array of tumor-microenvironmental interactions, resulting in metastasis promotion, which can be reduced by CSF-1R inhibition." (PMID 40760255, 2025). "TGCT is unique because the tumor itself is dependent on CSF1R signaling." (PMID 39782686, 2025). "Likewise, inhibition of CSF-1R in macrophages cultured with medium conditioned by the tumor cells led to a reduction in the amount of secreted VEGF-A." (PMID 40646332, 2025). "While strategies such as CSF-1R inhibition, immune checkpoint blockade, and nanotechnology-based interventions show potential in restoring immune function and inhibiting tumor progression, these approaches must be optimized to overcome TAM plasticity, spatial complexity, and delivery limitations." (PMID 41310829, 2025). "When CSF1R inhibition is combined with immune checkpoint blockade, particularly anti-PD-1 antibodies, murine models display enhanced immune activation and durable tumor responses." (PMID 40867316, 2025). "Additionally, treatments such as colony-stimulating factor-1 receptor (CSF-1R) inhibitors that target TAMs alter the tumor microenvironment and reduce immunological suppression." (PMID 41179937, 2025). "Regorafenib further augments this synergy by normalizing the tumor vasculature and immune microenvironment, while its inhibition of CSF1R and modulation of VEGFR2/3 promotes macrophage reprogramming and CD8+ T-cell activation, establishing a robust antitumor immune response." (PMID 41179689, 2025). "Immunosuppressive TAMs help to maintain a pro-tumor TME via CSF-1/CSF-1R signaling." (PMID 41228234, 2025). "Additionally, CSF1R is critical for microglial survival and proliferation, making it a potential therapeutic target to reduce microglia-mediated tumor promotion." (PMID 40076502, 2025).
tumor (continued). "These include combining CSF1R inhibitors with immune checkpoint inhibitors, chemotherapy, anti-angiogenic agents, or radiotherapy, aiming to synergistically overcome the immunosuppressive tumor microenvironment." (PMID 40821795, 2025). "While the mechanisms of tumor cell resistance are well understood, it remains unclear whether CSF1R inhibition alters the overall composition and dynamics of the GBM TME, and whether similar effects are observed in other types of brain tumors." (PMID 40800581, 2025). "Furthermore, the use of anti‐CSF1/CSF1R agents has demonstrated synergistic effects with ADT in managing PCa by reducing pro‐tumor CAM infiltration both in vitro and in vivo." (PMID 40007149, 2025). "These cancer-specific polarization patterns, along with CD68’s strong immune correlations, suggest tailored immunotherapy approaches - particularly combining polarization modulators (e.g., CSF-1R inhibitors) with PD-1 blockade - should be developed based on tumor-type macrophage profiles." (PMID 40918116, 2025). "CSF1R, a receptor tyrosine kinase, plays a critical role in the differentiation and maintenance of TAMs, particularly the M2-polarized subtype, which contributes to immune suppression and tumor progression." (PMID 40330466, 2025). "Strategies that deplete or repolarize TAMs—for instance, by inhibiting the CSF1R pathway—could dismantle the immunosuppressive shield and synergize with ICIs to unleash a more effective anti-tumor T-cell response." (PMID 41293237, 2025). "CSF1R, a receptor tyrosine kinase essential for macrophage survival and polarization, supports the differentiation of TAMs that secrete pro-angiogenic and growth factors, thereby promoting tumor progression and metastasis." (PMID 40297580, 2025). "Additionally, macrophage-derived IGF-1 activates IGF-1R and PI3K signaling pathways in tumor cells, which promote tumor recurrence following CSF-1R inhibition." (PMID 40076738, 2025). "In addition, the colony-stimulating factor-1 (CSF1)/CSF1 receptor (CSF1R) axis plays a multifaceted role in the tumor microenvironment (TME), with particular relevance to its function in the survival and activation of tumor-associated macrophages." (PMID 40052125, 2025). "CSF-1R facilitated the dissociation of the tumor cell adhesion molecule E-calmodulin from cytoskeletal proteins, which disrupted cell junctions and reduced the adhesion capacity, contributing to the ease of distant migration and proliferation of cancer cells away from their primary sites." (PMID 38303927, 2024). "Is CSF-1R differently regulated than other tumor cell membrane receptors?" (PMID 38254773, 2024). "Additionally, a comparative analysis between the administration of PLX3397 therapy at the initiation of RT and its administration 48 h following RT showed that early inhibition of CSF1R signaling augmented the efficacy of RT in restraining tumor growth." (PMID 39165639, 2024). "Since a similar PLX CSF1R inhibitor is currently FDA approved for a rare myeloid-derived tumor and has been well tolerated, this may be a more clinically translatable preconditioning regimen." (PMID 38516884, 2024). "In addition, anti-CSF1R was administered 10 days before tumor inoculation (D-10) to eliminate macrophages earlier and more thoroughly to further verify the importance of macrophages in the abdominal dissemination of GC." (PMID 38238529, 2024). "In addition to targeting CD47, it has been found that SIRPα–blocking antibodies combined with CSF-1R inhibitors can stimulate the activation of anti-tumor macrophages." (PMID 39169402, 2024). "Notably, the CSF-1R in CSCs contributes to tumor aggressiveness and therapeutic resistance through interactions with TAMs and the modulation of stemness features." (PMID 39457693, 2024).